LEP (leptin)
Diseases named in the same sentence as LEP in open-access papers (continued):
Sharing a sentence is not in itself a finding about the gene and the disease.
Obesity (continued). "For example, in obesity, high leptin levels are associated with the activation of the sympathetic ANS, as a compensatory mechanism against weight gain." (PMID 29329523, 2018). "In general, obesity is associated with increased leptin levels in the blood as well as the development of leptin resistance." (PMID 29391540, 2018). "Genetic variations in LEPR were already reported to be associated with a reduced capacity of leptin to regulate body weight and energy homeostasis, a process known as leptin resistance, which can lead to obesity-related phenotypes." (PMID 30126176, 2018). "DNAJC27 was found to be associated with leptin and resistin, adipokines known to be dysregulated in obesity, that stimulate inflammatory processes leading to metabolic disorders." (PMID 30131766, 2018). "Obesity-associated elevation of leptin also contributes to the increased susceptibility of asthma via modulation of Th2 and ILC2 response." (PMID 30233575, 2018). "Hypothalamic ER stress occurs under conditions of nutritional excess, such as obesity and type 2 diabetes, which are associated with leptin and insulin resistance." (PMID 30018241, 2018). "While leptin treatment is effective in obesity that is caused by leptin and leptin receptor genetic polymorphisms, these are rare (<5% of obese individuals)." (PMID 30373146, 2018). "In a prospective cohort study of Black and White participants, higher levels of pre-diagnostic leptin was independently associated with a lower risk of overall cancer mortality, and with reduced risk of obesity-related cancer mortality." (PMID 29662629, 2018). "Further, to complement the role of leptin and resistin and other obesity-associated factors in cell growth, long-term cell survival assay was performed." (PMID 29568521, 2018). "Such hypothalamic inflammation is associated with metabolic dysfunction, central leptin resistance, and maintenance of obesity." (PMID 30355312, 2018). "Amelioration of hyperleptinemia and leptin resistance had been demonstrated to be one key underlying mechanism of CB1R antagonism in alleviation of obesity." (PMID 29615900, 2018). "This article presents an Indian infant with severe early-onset obesity caused by a novel mutation in the leptin gene." (PMID 29217499, 2018). "This experimental study was designed to investigate the effects of Cucumis melo L. (Cucumis) on obesity-induced IR in genetically leptin-deficient Lepob/Lepob mice." (PMID 29636788, 2018). "Accordingly, hypothalamic insulin and leptin resistance is a hallmark of obesity and leads to hyperphagia and reduced locomotion." (PMID 29371411, 2018). "High levels of serum leptin and low levels of serum adiponectin are strongly correlated with obesity, a well-established risk factor for colorectal cancer (CRC)." (PMID 30379922, 2018). "Leptin or LepR deficiencies not only cause severe obesity but also abnormalities in haematopoiesis, immunity, angiogenesis, bone formation, blood pressure and reproduction." (PMID 29160594, 2018). "In conclusion, resveratrol reversed leptin resistance caused by diet-induced obesity in peripheral organs using tissue-specific mechanisms." (PMID 30441779, 2018). "Obesity caused by damaging mutations in LEP and LEPR display an autosomal recessive mode of inheritance while obesity caused by MC4R mutations exhibit variable penetrance (recessive or co-dominant)." (PMID 30442103, 2018). "Only in rare cases can monogenic etiologies of obesity be identified, such as mutations in genes encoding select hormones (LEP, POMC) or their receptors (LEPR, MC4R)." (PMID 30185666, 2018). "The development of resistance to leptin, a 16-kDa peptide hormone that controls body weight by reducing food intake and increasing energy expenditure, is a common hallmark of obesity." (PMID 30383868, 2018).
Obesity (continued). "Because of the close relationship between obesity, leptin, and OA, it is crucial to study the effects of weight loss and exercise intervention on serum leptin levels to improve the symptoms of OA patients." (PMID 29620639, 2018). "The adipose tissue-derived adipokines such as adiponectin, leptin, visfatin, resistin and adipsin are associated with obesity and obesity-related metabolic disorders including T2DM." (PMID 29785210, 2018). "A mutation in the leptin gene was found to result in massive obesity and type 2 diabetes in humans as well as in rodents." (PMID 30545408, 2018). "We evaluated 20 candidate variants in 4 genes previously shown to alter serum leptin and adiponectin levels for associations with obesity (BMI>30 kg/m2) and CRC risk." (PMID 30379922, 2018). "The inability of leptin to suppress food intake in diet-induced obesity, sometimes referred to as leptin resistance, is associated with several distinct pathological hallmarks." (PMID 29748097, 2018). "The observations that human and rodents with congenital leptin deficiencies are sterile and that anorexia and obesity modify the onset of puberty in opposite ways, led to the idea that leptin is an important player in reproduction." (PMID 29160594, 2018). "Accordingly, abnormal increases in the abundance (and possibly activity) of hypothalamic PTPases have been implicated in high-fat diet-induced obesity and central leptin resistance." (PMID 29632515, 2018). "Conversely, the positive relationship between KD, dissociation rates and obesity in the total cohort suggest that a decrease in IgG affinity for leptin (increase in KD) is associated with hyperleptinemia, BMI, and obesity." (PMID 29795184, 2018). "As a direct transcriptional product of STAT3, SOCS3 is commonly thought to play a pathophysiological role in obesity-associated leptin resistance." (PMID 29615796, 2018). "Leptin plays a major role in the regulation of energy homeostasis and has been strongly associated with obesity." (PMID 30224299, 2018). "Monogenic forms of obesity are rare and are usually characterized by early-onset obesity associated with endocrine disorders, mainly due to mutations in genes of the leptin/melanocortin axis involved in food intake regulation." (PMID 29880780, 2018). "In rodents, obesity is associated with leptin resistance due to decreased mRNA expression and translation of its receptor." (PMID 29867590, 2018). "Leptin resistance and consequently, hyperleptinemia, seems to be one of the major causes of obesity." (PMID 29636725, 2018). "Birth weight was also associated with AHRR (involved in cell growth and differentiation), HFI3A (obesity-associated gene) and LEP (appetite-related) methylation." (PMID 30096154, 2018). "Among 1764 participants with available biomarker data, each SD higher log-leptin was associated with a 54% reduced risk of total cancer mortality (HR: 0.46, 95% CI: 0.23 – 0.92) and obesity-related cancer mortality (HR: 0.55, 95% CI: 0.39-0.79)." (PMID 29662629, 2018). "Recent studies reported that inflammatory cytokines such as leptin, adiponectin, and IL-1β are involved in obesity-associated OA progression." (PMID 29843440, 2018). "In adulthood, Nnat null mice displayed decreased energy expenditure, blunted leptin sensitivity, and hyperphagia, resulting in obesity under high fat diet-feeding or associated with aging." (PMID 30279096, 2018). "This phenomenon has been reproduced in mice, as systemic administration of CNTF reduced hyperphagia and obesity in mice deficient with functional leptin (ob/ob mice) or leptin receptor (db/db mouse)." (PMID 30555354, 2018). "Despite intense research on this topic, elucidating how HFD causes leptin resistance, remains a major challenge in obesity research." (PMID 30185666, 2018). "The association of the LEP G2548A polymorphism and higher BMI levels, which was found in our study, was also reported in Tunisians with obesity." (PMID 30583468, 2018).
Obesity (continued). "Leptin is a pleiotropic cytokine that regulates numerous physiological processes and whose dysfunction is implicated in pathologies including obesity, diabetes, and cancer." (PMID 30186233, 2018). "Obesity is a modifiable risk factor of PC that is characterized by inflammation and high levels of the adipokine leptin, which was previously found to induce cancer proliferation and expansion of PCSC." (PMID 29719602, 2018). "Chga KO mice has higher level of leptin due to prolonged effect of insulin on Srebp-1c gene expression, causes obesity which was reversed by PST13." (PMID 29880906, 2018). "LEP G2548A has been associated with obesity and serum leptin levels in Turkish subjects and a study that reports a synergistic effect of LEP and LEPR polymorphisms on BMI, in a Han Chinese population." (PMID 30121879, 2018). "In conclusion, our study investigated the role of leptin and adiponectin in obesity and colorectal cancer using a candidate gene variant approach." (PMID 30379922, 2018). "As a consequence of a loss of leptin function, the db/db mice show many of the characteristics of type 2 diabetic patients, including obesity, hyperglycaemia, and insulin resistance." (PMID 29862294, 2018). "Leptin signaling in the liver is important for lipid metabolism and is impaired in obesity, and SNPs in Lepr in humans are associated with NAFLD." (PMID 29447215, 2018). "To investigate the mechanisms underlying the joint effect of DEHP and obesity on low testosterone levels, we determined the levels of leptin and oxidative stress in the testicular tissue." (PMID 29887939, 2018). "Obesity is associated with oxidative stress, a major factor in carcinogenesis, and with high leptin concentration." (PMID 30563501, 2018). "On the other hand, leptin or LepR deficiency increases appetites, energy uptake, and leads to obesity in animal models and humans." (PMID 30551684, 2018). "A study investigating the inflammatory characteristics of human IFP in knee OA and obesity demonstrated an overproduction of IL-6, which was associated with a decrease of local leptin secretion and an increase in adiponectin secretion." (PMID 29769086, 2018). "Because there is such a close link between obesity, leptin, and OA, it is crucial to study the effects of weight loss and exercise intervention on serum leptin levels to improve the symptoms of OA patients." (PMID 29620639, 2018). "Leptin signaling in obesity has also been associated with the production of numerous pro-inflammatory cytokines, whose signaling play important roles in the initial phases of controlling pneumococcal pneumonia." (PMID 29497602, 2018). "In conclusion, we report the second patient from India with a novel mutation of the LEP gene associated with severe obesity." (PMID 29217499, 2018). "Some studies have linked intake of a GF diet to reduced obesity and T2D and suggested a role in reducing leptin- and insulin-resistance and increasing beta-cell volume." (PMID 30428550, 2018). "The most amenable large-animal model for obesity is the pig and there is a swine breed, the Iberian pig, which is a specific model for studies on obesity associated with leptin resistance." (PMID 30288483, 2018). "The spontaneous leptin mutation model ob/ob mice develop severe diabetes with marked hyperglycemia and a propensity to overeat, resulting in obesity and the development of hepatic steatosis." (PMID 28643267, 2018). "Testosterone signals through the androgen receptor (AR) and AR knockout mice develop obesity, suggesting a functional association between AR and leptin signaling." (PMID 29895265, 2018). "Leptin (LEP) and fat mass and obesity-associated (FTO) alleles are known to influence body fat mass in humans, potentially via effects on appetite." (PMID 30241328, 2018). "Further research will explore the association between sleep duration and leptin/ghrelin in children and adolescents to deeply dig out underlying mechanisms of obesity." (PMID 29693616, 2018).
Obesity (continued). "In controls and diabetic patients, the association rates of leptin IgG correlated negatively with obesity and diabetes markers, respectively." (PMID 29795184, 2018). "Poor sleep quality is associated with low leptin and high ghrelin, which are likely to increase appetite, and consequently the risk of obesity." (PMID 30463242, 2018). "Leptin and Cancer: Leptin can increase cancer risk and stimulate the aggressiveness of cancer cells, including the obesity-related cancers of the breast and prostate." (PMID 29587359, 2018). "Since leptin modulates the immune system, as well as insulin resistance and metabolic disorders like metabolic syndrome and obesity, all RA-associated conditions, this adipokine represents an attractive therapeutic target for RA." (PMID 29910742, 2018). "Other obese models such as the ob/ob and db/db, have a defect in leptin or the leptin receptor, which prevent leptin regulation on obesity-associated signaling pathways in cancer." (PMID 30567335, 2018). "Mutations in members of the leptin-regulated melanocortin circuit have been shown to result in human obesity." (PMID 30068297, 2018). "Congenital leptin deficiency due to mutations of the leptin gene is a rare cause of early-onset obesity with less than 50 cases reported to date." (PMID 29217499, 2018). "Many studies have concluded that plasma leptin and adiponectin are associated with obesity and MetS, and can be used as diagnostic markers for MetS." (PMID 30305835, 2018). "Large prospective studies are needed to elucidate the exact effects of bariatric-induced weight loss on the thyroid function of patients with obesity; and their potential underlying associations to key adipokines, such as leptin." (PMID 30197625, 2018). "It has been previously proposed that the failure of high circulating leptin levels in obesity to promote weight loss defines a state of so-called “leptin resistance”24,25,27, whereas the etiology of which remains poorly defined." (PMID 29343842, 2018). "Similar phenomenon has been reported in human patients showing different degrees of obesity by carrying different mutated leptin genotypes." (PMID 30551684, 2018). "PTP1B have been linked to central leptin resistance in humans as well as in a variety of animal models of obesity and aging." (PMID 30692905, 2018). "Both high levels of serum leptin and low levels of serum adiponectin are strongly correlated with obesity, which is a well-established risk factor for colorectal cancer (CRC)." (PMID 30379922, 2018). "Intriguingly, leptin deficiency is linked to the early-onset of obesity, indicating that ratio of leptin to insulin is fundamental in the homeostatic balance of fat and glucose metabolism." (PMID 30405405, 2018). "Most notably, human obesity has been associated with mutations in leptin (LEP), leptin receptor (LEPR), prohormone convertase 1 (PC1), proopiomelanocortin (POMC) and melanocortin-4 receptor (MC4R)." (PMID 30068297, 2018). "Our work provides compelling evidence indicating that an increased leptin level plays a crucial role in the development of obesity-associated SLE." (PMID 30169503, 2018). "Leptin and oxytocin have each been strongly associated with obesity and T2D and psychiatric conditions in previous studies." (PMID 29596446, 2018). "In mice, those fed a higher dietary sodium intake had associated with leptin resistance and obesity." (PMID 32153908, 2018). "In fact, affinity kinetics properties of leptin-reactive IgG were found to be associated with plasma leptin levels, as well as with several anthropometric and biochemical parameters of obesity and diabetes." (PMID 29795184, 2018). "As observed in our previous study, by controlling obesity, tumor growth is restricted partly through normalization in the serum levels of obesity-associated factors such as leptin and resistin." (PMID 29568521, 2018).
Obesity (continued). "Further insights into the pathophysiological role of leptin in the immune system and in obesity-associated disorders will be of great importance for the development of novel therapeutic approaches for these diseases." (PMID 29910742, 2018). "To conclude, this study investigates the role of increased levels of obesity-associated important adipokines leptin and resistin in melanoma growth and the outcome of DTIC-based therapy." (PMID 29568521, 2018). "Only in a few particular cases do we know about the mechanism involved and have the specific tools to resolve the problem (i.e., in the case of leptin deficiency, which affects a small number of individuals, obesity can be treated with leptin injections)." (PMID 29329236, 2018). "Both db/db and ob/ob mice are characterized by obesity and overeating as a result of the loss of leptin signaling, and they develop hyperglycemia, impaired glucose tolerance, and hyperinsulinemia." (PMID 29434323, 2018). "Results of the analysis stratified by obesity status, showed that high levels of both adiponectin and medium level of leptin were significantly associated with development of CKD among non-obese participants but not among obese participants." (PMID 30236068, 2018). "Leptin-resistant conditions, characteristic for obesity, lead to a loss of hypothalamus control of appetite and feeding behavior, exacerbating the already excessive body weight gain." (PMID 29849871, 2018). "Treatment of both obese leptin-deficient (ob/ob) and diet-induced obesity (DIO) mice with norfloxacin and ampicillin for 2 weeks improved fasting blood glucose and oral glucose tolerance." (PMID 30030441, 2018). "The association of the risk allele “A” with higher leptin to fat mass ratio, higher levels of thyrotropin and lower resting energy expenditure is a likely explanation for its predisposition to increased obesity risk." (PMID 29343214, 2018). "Leptin replacement is remarkably effective in treating rare forms of human obesity due to mutation of the leptin gene." (PMID 29434574, 2018). "Baver and associates have shown that diet-induced obesity in mice is associated with a failure of leptin to inhibit the orexigenic effects of AgRP neuronal activity." (PMID 29867590, 2018). "On the other hand, it is well known that exercise and/or exercise training can reverse leptin resistance associated with HFD-induced obesity in rodents." (PMID 30343561, 2018). "Long-term exposure to hyperleptinemia, observed in obesity, has been associated with decreased NK immune activity possibly due to the development of leptin resistance." (PMID 29910742, 2018). "Over the last decades, enhanced circulating leptin levels and decreased adiponectin levels emerged as one of the mechanisms underlying the cardiometabolic sequelae in obesity." (PMID 29073286, 2017). "Rodents with leptin or OB-Rb mutations show several phenotypes including infertility, hyperphagia, obesity, and reduced energy expenditure as well as reduced somatotrope numbers." (PMID 28771488, 2017). "These SS offspring developed obesity due to increased feed efficiency despite a reduced energy intake associating with reduced leptin signalling in ARC as indicated by reduced fasting pSTAT3 activity." (PMID 28092346, 2017). "We further reveal a potential role of WISP1 in obesity consistent with its upregulation in the epididymal adipose tissue from mice on a high fat diet according to30 as well as in leptin-deficient ob/ob mice." (PMID 28496206, 2017). "Although leptin replacement does dramatically reduce leptin-deficient obesity, the results of clinical trials assessing the ability of recombinant leptin to reduce body weight in patients with normal levels of leptin have been underwhelming." (PMID 28350856, 2017). "Loss-of-function mutations in the leptin or ObR genes or genetic ablation of leptin’s central signaling results in severe, early-onset obesity." (PMID 28270795, 2017).